UBE2R2 (ubiquitin conjugating enzyme E2 R2)
Description:
E2 ubiquitin-conjugating enzyme that accepts ubiquitin from an E1 ubiquitin-activating protein, and catalyzes its covalent attachment to other proteins by an E3 ubiquitin-protein ligase complex. In vitro catalyzes monoubiquitination and 'Lys-48'-linked polyubiquitination. Works in collaboration with various Cul1-RING and Cul2-RING E3 ligase complexes. May be involved in degradation of katenin.
Synonyms: CDC34B; UBC3B; FLJ20419; MGC10481; E2-CDC34B
Tractability: Small molecule: a structure with a bound ligand is known. PROTAC: ubiquitination databases record sites on it; its protein half-life has been measured.
Gene: Protein-coding gene on chromosome 9 (33,817,160 to 33,920,399, forward strand). Ensembl gene ENSG00000107341.
Subcellular location (Human Protein Atlas): Nucleoli; Nucleoplasm; Cytosol
Pathways (Reactome):
Immune System: Antigen processing: Ubiquitination & Proteasome degradation
Metabolism of proteins: Synthesis of active ubiquitin: roles of E1 and E2 enzymes
Gene Ontology:
Molecular function: protein binding; ubiquitin conjugating enzyme activity; ubiquitin-protein transferase activity
Biological process: protein K48-linked ubiquitination; protein monoubiquitination; protein polyubiquitination; protein ubiquitination
Cellular component: cytosol
Genetic constraint (gnomAD): Loss-of-function variants: 1 observed, 24.93 expected, observed/expected ratio (o/e) 0.0401, 90% interval 0.013 to 0.19. The upper end of that interval is the gene's LOEUF score, 0.19, which puts it in group 1 of 6, group 1 being the genes least tolerant of losing a copy. Missense variants: 98 observed, 293.38 expected, observed/expected ratio (o/e) 0.33, 90% interval 0.28 to 0.4. Synonymous variants: 102 observed, 115.49 expected, observed/expected ratio (o/e) 0.88, 90% interval 0.75 to 1.04.
Homologues: Orthologues: chimpanzee UBE2R2 (100% identical), dog UBE2R2 (100% identical), guinea pig UBE2R2 (100% identical), macaque UBE2R2 (100% identical), mouse Ube2r2 (100% identical), pig UBE2R2 (100% identical), rabbit UBE2R2 (100% identical), rat Ube2r2 (100% identical), tropical clawed frog ube2r2 (99% identical). Paralogues in human: CDC34 (80% identical), UBE2G1 (38% identical), UBE2G2 (34% identical), UBE2B (26% identical), UBE2A (25% identical), UBE2I (25% identical), UBE2N (24% identical), UBE2O (24% identical), UBE2T (24% identical), UBE2K (24% identical), UBE2NL (23% identical), UBE2W (23% identical), and 12 more.
Diseases named in the same sentence as UBE2R2 in open-access papers:
UBE2R2 is named in the same sentence as 10 diseases in open-access papers, as found by Europe PMC text mining. Sharing a sentence is not in itself a finding about the gene and the disease. The quoted sentences say what the papers report.
B cell lymphoma (1 paper, 2019). "To address this question in an unbiased manner, we performed genome-wide CRISPR knockout screens in the NALM-6 pre-B cell lymphoma line with the previously reported EKO sgRNA library to identify genes that exhibit synthetic lethality with the loss of UBE2R1 and/or UBE2R2." (PMID 31868589, 2019).
brain tumors (1 paper, 2025). "UBE2R2 expression has been linked to brain tumors, and its targeting by HAM/TSP IgG may be associated with the neurological disorders observed in these patients." (PMID 41303346, 2025).
breast carcinoma (1 paper, 2024). "We examined a panel of cell lines for their steady-state levels of UBE2R1 and UBE2R2 and noticed low levels of UBE2R2 in multiple cell lines including the breast cancer cell line MDA-MB-468 (Excel File S2)." (PMID 38382526, 2024).
epithelial ovarian cancer (1 paper, 2024).
cancer (1 paper, 2020). A tumor composed of atypical neoplastic, often pleomorphic cells that invade other tissues. "We found that 30 of these genes which included Nckap1l, Ncf1, Pla2g15, Unc93b1, Lrrc33, Rgs10, Gmfg, Rbm25, C3ar1, Ccdc88b, Fam105a, Gng11, Phc1, Rasa4, Dag1, Tyrobp, Tmsb4x, Cfp, Prkd1, Gp49a, Trem2, C1qc, Lyz2, Igfbp7, Rab30, Cxcl16, Egfl7, Ube2r2, Pltp, and Cfb, showed a relation with cancer." (PMID 32812032, 2020).
UBE2R2 also shares sentences with these, for which no sentence is quoted: adenoma (1 paper); bipolar disorder (1); glioma (1); neurological disorders (1); tumor (1).